CXCL13 (C-X-C motif chemokine ligand 13)
Diseases named in the same sentence as CXCL13 in open-access papers (continued):
Sharing a sentence is not in itself a finding about the gene and the disease.
tuberculosis (3 papers, 2014 to 2025). A chronic, recurrent infection caused by the bacterium Mycobacterium tuberculosis. "The absence of CXCR5/CXCL13 axis can lead to increased susceptibility to tuberculosis." (PMID 40264781, 2025). "For instance, CXCL13 promotes the recruitment of CXCR5+ follicular B- and T helper cells into the M. tuberculosis–infected lung, where they form ectopic lymphoid follicles that support protective immunity against TB." (PMID 34561226, 2021).
visceral leishmaniasis (3 papers, 2012 to 2025). A severe form of leishmaniasis characterized by irregular bouts of fever, substantial weight loss, swelling of the spleen and liver, and anemia (which may be serious). "The data presented herein suggest that natural infection with Leishmania infantum is associated with the impairment of follicular dendritic cells, CXCL13 expression, B cell migration and germinal center formation and associates these changes with severe clinical forms of visceral leishmaniasis." (PMID 22242159, 2012). "In human visceral leishmaniasis infections reduce lymphoid tissue production of CXCL13 results in impaired B/T cell interaction leading to sub-optimal adoptive immunity." (PMID 27095356, 2016). "In chronic infections such as visceral leishmaniasis, lymphoid follicle disorganization results in the impairment of lymphocyte migration into the lymphoid follicle secondary to follicular dendritic cell death, as well as decreased CXCL13 production." (PMID 41210940, 2025). "Certain pathological processes may be responsible for the disruption of this CXCL13-dependent cross-stimulation loop between B cells and follicular dendritic cells during visceral leishmaniasis." (PMID 22242159, 2012).
adenoma (2 papers, 2023 to 2024). A neoplasm arising from the epithelium. "In contrast, a significant increase of chemokine C-X-C motif ligand 13 (CXCL13) was observed solely in CD8+ NK cells in both adenoma and carcinoma samples in our analyses." (PMID 38023180, 2023).
amyloid (2 papers, 2022 to 2025). "Overall, we found that depleting and repopulating microglia causes overexpression of microglial Cxcl13 with disparate effects on Tau and amyloid pathologies." (PMID 35787714, 2022). "In addition, in the 3xTg AD mice model microglial re-population following depletion led to increased CXCL13 expression, with differential changes in tau phosphorylation and amyloid pathology." (PMID 40313591, 2025).
amyotrophic lateral sclerosis (2 papers, 2023 to 2024). Amyotrophic lateral sclerosis (ALS) is a neurodegenerative disease characterized by progressive muscular paralysis reflecting degeneration of motor neurons in the primary motor cortex, corticospinal tracts, brainstem and spinal cord. "In a mouse model of amyotrophic lateral sclerosis, CXCL13/CXCR5 signalling was strongly up-regulated among motor neurons, but silencing the axis resulted in increased motor neuron loss." (PMID 37765263, 2023).
aseptic meningitis (2 papers, 2015 to 2025). Inflammation of the membranes surrounding the brain and spinal cord without a bacterial pathogen. "CXCL13 in cerebrospinal fluid is a potential prognostic marker for aseptic meningitis." (PMID 26517519, 2015).
Atrophy (2 papers, 2023 to 2026). Any weakening or degeneration, especially through lack of use. "The diseased mice displayed splenic atrophy and systemic inflammation, with elevated serum IGFBP-1 and CXCL13 levels." (PMID 41562619, 2026).
autoimmune hemolytic anemia (2 papers, 2015 to 2016). Autoimmune hemolytic anemia (AIHA) is an autoimmune disorder in which various types of auto-antibodies are directed against red blood cells causing their survival to be shortened and resulting in hemolytic anemia. "Recently, CXCL13 has been reported to participate in SLE-related autoimmune hemolytic anemia." (PMID 27672667, 2016).
autoimmune myocarditis (2 papers, 2020 to 2025). Autoimmune myocarditis is an autoimmune disease that affects the heart. "The expression levels of interleukin‐21 and CXCL13 were elevated in serum and spleen of rats with autoimmune myocarditis." (PMID 32416035, 2020). "The expression levels of IL‐21 and CXCL13 were elevated in the serum and spleen of rats with autoimmune myocarditis." (PMID 32416035, 2020). "Furthermore, we also observed the expression of cytokine IL‐21 and chemokine CXCL13 in the spleen of rats with autoimmune myocarditis." (PMID 32416035, 2020). "Furthermore, our findings suggested that Tfh cells could generate a large number of cytokines IL‐21 and CXCL13 to stimulate B cells to produce a large number of autoantibodies, which ultimately accelerates the development of autoimmune myocarditis." (PMID 32416035, 2020). "In autoimmune myocarditis mice models, increased mRNA and protein expression of CXCR5 and CXCL13 were found in myocardial tissue." (PMID 40705171, 2025).
autoimmune pancreatitis (2 papers, 2022 to 2024). "Meanwhile, according to a study conducted on autoimmune pancreatitis (AIP), a common feature in IgG4-RD, it is observed that LTα and LTβ are overexpressed and positively correlate with CXCL13 expression." (PMID 38911857, 2024).
Behçet's disease (2 papers, 2021 to 2025). "The levels of CXCL13 in aqueous humor samples from patients with VKHS are significantly higher than those from patients with leukodystrophy Behcet’s disease (BD) and patients with human leukocyte antigen (HLA)-B27-associated uveitis." (PMID 39449345, 2025).
bladder pain syndrome (2 papers, 2022 to 2025). "CXCL13, a B cell chemokine, and its receptor CXCR5 form a chemotactic axis whose aberrant activation drives B cell-mediated immune responses, thereby promoting inflammatory processes and endothelial injury, which are implicated in the pathophysiology of interstitial cystitis/bladder pain syndrome." (PMID 41196851, 2025).
bladder tumor (2 papers, 2021 to 2025). "To further investigate potential interactions between CXCL13 CAR T cells and endogenous immune cells, we employed the MB49‐CD19 bladder tumor model, which is known for heightened immune infiltration." (PMID 40492496, 2025).
Brain atrophy (2 papers, 2013 to 2021). Partial or complete wasting (loss) of brain tissue that was once present. "In this light, the levels of CXCL13 correlated well with the QIgM values, an observation that could be consistent with the recent suggestion that IgM oligoclonal bands may track with brain atrophy and lesion load." (PMID 24278364, 2013). "The CHI3L1 (chitinase-3-like protein 1) level in the CSF was strongly correlated with brain atrophy, and the CSF levels of CXCL1, MMP-9, CCL22, CXCL13, and CXCL10 were correlated with the development of new lesions in T2 MRI." (PMID 34602928, 2021).
brain injury (2 papers, 2022 to 2023). Acute and chronic (see also brain INJURIES, CHRONIC) injuries to the brain, including the cerebral hemispheres, CEREBELLUM, and brain STEM. "The expression of chemokines (e.g., CCL2, CCL5, CXCL10, and CXCL13) was also elevated in peripheral blood after brain injury and strongly associated with poor prognosis of TBI patients." (PMID 37208955, 2023).
carotid atherosclerosis (2 papers, 2021 to 2024). A thickening and loss of elasticity of the walls of carotid arteries that occur with formation of atherosclerotic plaques. "Patients with carotid atherosclerosis showed increased plasma levels of CXCL13, where CXCL13 exerted anti-apoptotic effects and counteracted the suppressive effects of IL-1b on collagen synthesis in smooth muscle cells (SMCs)." (PMID 38880863, 2024). "Increased levels of plasma CXCL13, also known as B-cell-attracting chemokine 1 (BCA1), were previously reported in patients with carotid atherosclerosis." (PMID 34948275, 2021).
Cerebral ischemia (2 papers, 2018 to 2024). Restriction of arterial blood supply to the brain associated with insufficient oxygenation to support the metabolic requirements of the tissue. "CXCL12 and CXCL13 have been associated with a deleterious role during cerebral ischemia attracting lymphocytes." (PMID 30258527, 2018). "During the CI/R phase, CXCL5 recruits inflammatory cytokines at sites of cerebral ischemia and disrupts cerebral vasculature; activated cerebral vasculature can exacerbate cerebral neuronal injury by expressing CXCL13; meanwhile, XCL-1 and CCL2/MCP-1 promote neuronal apoptosis." (PMID 39206161, 2024). "Inhibition of CXCL5, CXCL13, XCL-1,and CCL2/MCP-1 during the cerebral ischemia/reperfusion (CI/R) phase of VaD holds promise as a therapeutic strategy to mitigate microglial activation and minimize neurological injury." (PMID 39206161, 2024).
chronic endometritis (2 papers, 2022 to 2024). A non-granulomatous or granulomatous chronic inflammation of the endometrium. "Kitaya found the aberrant expression of CXCL13 in the endometrium of patients with chronic endometritis." (PMID 39456064, 2024). "Studies have found that the chemokines CXCL1 and CXCL13 are abnormally expressed in female infertility patients with chronic endometritis." (PMID 36003498, 2022).
chronic Hepatitis C (2 papers, 2010 to 2017). "Additionally, serum CXCL13 levels were found to be elevated in chronic hepatitis C virus infection compared with HC and expression of CXCL13 protein was evident in inflammatory cells within portal tracts and strongly correlated with CD20+ B-cell numbers." (PMID 28386259, 2017).
cryoglobulinemia (2 papers, 2014 to 2021). Cryoglobulinemia is a type of vasculitis that is caused by abnormal proteins (antibodies) in the blood called 'cryoglobulins.' At cold temperatures, these proteins become solid or gel-like, which can block blood vessels and cause a variety of health problems. "Subsequently, the significance of these parameters (CXCL13 serum levels, age, disease duration, rheumatoid factor, hypocomplementemia, cryoglobulinemia, purpura, and high disease activity score) was further tested in multivariate analysis." (PMID 34484201, 2021).
dementia (2 papers, 2023). Loss of intellectual abilities interfering with an individual's social and occupational functions. "CXCL13 is a B-lymphocyte chemotaxis factor and contributes to an inflammatory response by activating astrocytes via CXCR5 in a neuralgia model, but there are no reports of AD-type dementia." (PMID 37978479, 2023).
demyelinating disease (2 papers, 2023). A broad group of disorders that affect the myelin sheaths that cover the neurons. "Discovering methods or molecules able to decrease CXCL13 secretion could expand therapeutic options in demyelinating diseases, as tissue samples from patients with MS and its murine model show increased CXCL13 synthesis in glial cells." (PMID 37765263, 2023).
demyelination (2 papers, 2019 to 2023). "Taken together, these results indicate that demyelinating B7-2KO nerves exhibit pro-inflammatory milieu, which is related to the selective CXCL13 expression and inflammatory demyelination." (PMID 31712675, 2019).
diabetic neuropathy (2 papers, 2015 to 2020). A chronic, pathological complication associated with diabetes mellitus, where nerve damages are incurred due to diabetic microvascular injury involving small blood vessels that supply these nerves, resulting in peripheral and/or autonomic nerve dysfunction. "For example, chemokine CXCL13 (C-X-C motif chemokine ligand 13) and its receptor CXCR5 (C-X-C chemokine receptor type 5) associated with inflammatory response have been demonstrated directly to be a pivotal regulator in the pathogenesis of painful diabetic neuropathy via ERK pathway." (PMID 32523943, 2020). "Our results suggest that, at day 7, CXCL11 and CXCL13 are not involved in STZ-induced diabetic neuropathy." (PMID 25789329, 2015). "This study verifies that, in streptozotocin-induced diabetic neuropathy, the spinal protein levels of CXCL1, CXCL5, CXCL9, and CXCL12, but not CXCL11 and CXCL13, are upregulated." (PMID 25789329, 2015).
eczema (2 papers, 2019 to 2026). "Eczema was associated with decreased concentrations of IFNα, IFNγ, TSLP, CXCL9, and CXCL13, but increased concentrations of CCL18 and Galectin-3." (PMID 31998285, 2019). "In addition, eczema was associated with decreased concentrations of IFNα, IFNγ, TSLP, CXCL9, and CXCL13, but with increased concentrations of CCL18 and Galectin-3." (PMID 31998285, 2019).
emphysema (2 papers, 2019 to 2022). "Emphysema patients, but not subjects with bronchiolitis, were associated with enhanced B-cell homing and activation pathways and the expression of genes such as CXCL13, CCL19 and POU2AF1 correlated with emphysema severity." (PMID 35820851, 2022).
endometriosis (2 papers, 2021 to 2022). The growth of functional endometrial tissue in anatomic sites outside the uterine body. "Additionally, in the eutopic endometrium with both endometriosis and CE, the expression level of CXCL13, a pro-inflammatory chemokine involved in the selective extravasation of B cells, is upregulated." (PMID 36359553, 2022). "In addition, some identified hub genes of the EC (TAGLN, GATA6, CDH3, CLU, COL8A1, MYH11, MYOCD) and EU (CXCL13, DDK-1, KLF4, CYP2E1, CYP4B1 and PROK1) have been reported be associated with endometriosis." (PMID 34522169, 2021). "Endometrial CXCL13 expression may play an important role in the pathophysiology of endometriosis." (PMID 34522169, 2021).
Facial palsy (2 papers, 2017 to 2024). Facial nerve palsy is a dysfunction of cranial nerve VII (the facial nerve) that results in inability to control facial muscles on the affected side with weakness of the muscles of facial expression and eye closure. "In our controls, we had 19 cases of idiopathic cases which all showed negative CSF CXCL13, reinforcing the strength of the CXCL13 diagnostic test in uncertain cases of facial palsy." (PMID 28859668, 2017). "Median CXCL13 concentrations in the CSF of patients with TBEV was 8.7 pg/ml while inflammatory diseases, facial palsy of unknown origin, primary headache, and other diseases had median CXCL13 levels of 4.5 pg/ml." (PMID 28859668, 2017).
gastric adenocarcinoma (2 papers, 2019 to 2025). "Previous research had reported that CXCL13 is associated with CRC infiltration by distinct T cell subsets, and CXCL11 is a member of the confirmed prognostic model of gastric adenocarcinoma." (PMID 31689990, 2019).
gastric adenoma (2 papers, 2018 to 2023). A neoplastic polyp that arises from the stomach. "In gastric adenomas, homeostatic chemokines (including CXCL13, CCLL9 and CCL21) were associated with the formation of TLS." (PMID 38110876, 2023).
gastric MALT lymphoma (2 papers, 2015 to 2019). "Taken together, this shows that CXCL13 might be one of the key cytokines involved in the development of gastric MALT lymphoma associated with H. suis infection." (PMID 25889172, 2015). "It has been shown that the expression of CXCL13 is significantly upregulated in gastric MALT lymphoma in both humans and mice." (PMID 25889172, 2015).
gastric tumours (2 papers, 2018 to 2025). "Homeostatic chemokines play a central role in the development of secondary lymphoid organs and TLSs,4, 12 and our earlier data revealed transcripts for Cxcl13, Ccl19, Ccl21 and Cxcl12 in laser microdissected TLSs from 6‐month‐old gp130F/F mice with well‐established gastric tumours." (PMID 29417587, 2018).
heart failure (2 papers, 2021 to 2025). Inability of the heart to pump blood at an adequate rate to meet tissue metabolic requirements. "The chemokine CXCL13 and its receptor CXCR5 play a significant role in cardiac remodeling, and their expression is markedly increased in experimental models of heart failure." (PMID 40650190, 2025).
Hyperglycemia (2 papers, 2019 to 2020). An increased concentration of glucose in the blood. "Instead, salivary gland dysfunction was associated with hyperglycemia and elevation of serum IL1β, IL16, and CXCL13." (PMID 31784615, 2019). "In this study, CXCL13, a typical chemokine for recognizing and recruiting CXCR5+ cells 15, was elevated in retina at the setting of hyperglycemia, probably facilitating migration of Tfh cells into diabetic retinae." (PMID 32226551, 2020).
hyperuricemia (2 papers, 2024 to 2025). An abnormally high level of uric acid. "At the molecular level, studies further demonstrate that hyperuricemia induces oxidative stress, endothelial dysfunction, and systemic inflammation, with hepatic LPCAT3 and CXCL‐13 upregulation driving lipid disturbances, characterized by elevated triglycerides and LDL‐C and reduced HDL‐C." (PMID 41287972, 2025).
idiopathic pulmonary artery hypertension (2 papers, 2016 to 2021). "Chemokine CXC ligand 13 (CXCL13) has been implicated in perivascular inflammation and pulmonary vascular remodeling in patients with idiopathic pulmonary artery hypertension (IPAH)." (PMID 26927848, 2016).
infectious encephalitis (2 papers, 2018 to 2022). An acute infectious process that affects the brain tissue. "The subgroup analysis results are only available for the infectious encephalitis group, which, similar to the overall effect, does not implicate any significant alteration in CXCL13 concentration (SMD, -0.52; 95% CI, -2.13–1.10; P = 0.53)." (PMID 36048783, 2022).
kidney damage (2 papers, 2022 to 2025). "We therefore expected to seek a serological assessment for early indication of kidney damage in SLE patients by evaluating the diagnostic efficacy of CXCL13 and its regulated CXCR5+ T cells in LN." (PMID 41164191, 2025). "This biphasic effect indicates illustrate that the normal expression of CXCL13 is important for maintaining the homeostasis of the immune system, and that both deficiency and high expression of CXCL13 may lead to kidney damage." (PMID 41164191, 2025). "There seems to be a contradiction between elevated serum CXCL13 and CXCL13 deficiency both leading to kidney damage in mice, which may be caused by the difference in the primary role of CXCL13 in the healthy and diseased states." (PMID 41164191, 2025). "An increase in B cells’ CXCR5 expression has been demonstrated when high levels of serum CXCL13 are detected in patients with SLE and nephropathy." (PMID 35663936, 2022).
liver fibrosis (2 papers, 2020 to 2025). "RANTES is involved in the inflammatory processes during the progression of liver fibrosis, and CXCL13 controls circulation and redistribution of B cells in lymphoid organs." (PMID 32719658, 2020).
lymphopenia (2 papers, 2021 to 2023). Reduction in the number of lymphocytes. "Notably, elevated IL-10 not only coincided with the occurrence of lymphopenia but, also, with elevated levels of CXCL13." (PMID 34960627, 2021). "Our recent study found that interleukin-10 (IL-10) and CXCL13 were obviously elevated in sera from mice infected with FMDV and were related to lymphopenia and the progression and severity of the disease." (PMID 37047294, 2023).
malaria (2 papers, 2014 to 2023). Malaria is a serious and sometimes fatal disease caused by a parasite that commonly infects a certain type of mosquito which feeds on humans. "In pregnancy-associated malaria, chemokines such as CXCL-4, CXCL-13, CXCL-16, and CCL-24 play critical roles in leucocyte trafficking to tissue sites in the infected placenta where inflammatory reactions are active." (PMID 36689438, 2023).
myositis (2 papers, 2022 to 2023). "Interestingly, a tissue-specific subpopulation of CD138+ plasma cells and CXCL12+/CXCL13+CD20+ B cells common to ASyS myositis were identified." (PMID 35612662, 2022). "Our findings on muscle specimens from patients with myositis are comparable with inflammatory central nervous system disorders in that increased levels of BAFF, CXCL-12, and CXCL-13 are observed." (PMID 37731487, 2023).